ARID1A (AT-rich interaction domain 1A)
Diseases named in the same sentence as ARID1A in open-access papers (continued):
Sharing a sentence is not in itself a finding about the gene and the disease.
triple-negative breast carcinoma (9 papers, 2019 to 2026). An invasive breast carcinoma which is negative for expression of estrogen receptor (ER), progesterone receptor (PR), and human epidermal growth factor receptor 2 (HER2). "Here, we show that female patients with ARID1A‐mutated triple negative breast cancer (TNBC) exhibit a higher bone metastasis incidence." (PMID 42191692, 2026). "ARID1A is an ambiguous regulator in cancer biology, as its role in triple-negative breast cancer (TNBC) is context-dependent." (PMID 41514650, 2025). "The downregulation of ARID1A, known for its potential in DNA repair and immune response modulation, in triple-negative breast cancer, marks it as a target for immune checkpoint inhibitors." (PMID 38745208, 2024). "Mechanistically, both nuclear and cytoplasmic protein analyses and immunofluorescent localisation assays confirm that ARID1A recruits the Hippo pathway effector YAP into the nucleus in human triple-negative breast cancer cells." (PMID 37173914, 2023). "Moreover, the downregulation of ARID1A promoted migration and invasion in both human triple-negative breast cancer cells and xenograft models through the Hippo/YAP signalling axis." (PMID 37173914, 2023). "The present study aims to investigate whether and how ARID1A contributes to the metastatic heterogeneity of triple-negative breast cancer." (PMID 37173914, 2023). "Furthermore, we utilised the triple negative breast cancer cell line, CAL-51, which does not express ARID1A, complemented these cells with vectors expressing GFP or GFP-ARID1A WT and assessed the effect of KLF5 inhibition on their growth." (PMID 39779698, 2025).
adenoma (8 papers, 2015 to 2025). A neoplasm arising from the epithelium. "In this case, we propose that the patient’s germline ATM mutation and tumour-specific ARID1A mutation contributed to adenoma formation and malignant transformation." (PMID 41146957, 2025). "Genes commonly modulated in HAs IV and VI were compared to those selectively modulated in adenoma V, which presented a second hit in ARID1A." (PMID 39408812, 2024). "As with ARID2, the TSG and candidate drivers of colorectal adenomas ARID1A, and ARID1B are frequently mutated in MSI tumours including adenomas." (PMID 34843512, 2021). "Eleven somatic mutations were located in genes involved in the early adenoma formation (APC, RNF43 and CTNNB1), whereas two mutations were detected in genes involved in later stages (ARID1A, NRAS)." (PMID 31285513, 2019). "In addition, frequent mutations in epigenetic modifiers (truncating mutations in ARID1A, MLL3, and PBRM1) were observed as clonal or adenoma-specific events." (PMID 26336987, 2015).
BAFopathy (8 papers, 2021 to 2024). Disorder caused by mutations in the various subunits composing the BAF complex. "We detected a predominantly hypermethylation profile; the highest percentage of overlap in DMPs was with BAFopathies (11%, including ARID1A, ARID1B, SMARCB1, SMARCA2, SMARCA4), and CHARGE syndrome (10%, CHD7)." (PMID 38351292, 2024). "Other combined episignatures, such as for the BAFopathy (genes: ARID1A, ARID1B, SMARCB1, SMARCA2 and SMARCA4) episignature, are already proving their clinical utility." (PMID 38787418, 2024). "BAFopathy presented with a ~4% overlap, including ARID1A, ARID1B, SMARCB1, SMARCA2, and SMARCA4, and includes several neurodevelopmental disorders caused by variants in genes within the BRG1/BRM-associated factor (BAF) complex." (PMID 37762546, 2023). "This analysis showed that TRIP12 is most closely related to the CSS9 (SOX11), BAFopathy (ARID1A, ARID1B, SMARCB1, SMARCA2, SMARCA4) and MRD23 (SETD5) episignatures." (PMID 36430143, 2022). "Typical CSS, which is also referred to as BAFopathy, is caused by variants in the subunit of BAF complex, including ARID1A (OMIM#603024), ARID1B (OMIM#614556), SMARCA4 (OMIM#603254), SMARCB1 (OMIM#601607), ARID2 (OMIM#609539), and SMARCE1 (OMIM#603111)." (PMID 35938035, 2022). "Notably, JARID2 exhibited the highest overlap with CHARGE (~7%, CHD7), BAFopathy (~4%, including ARID1A, ARID1B, SMARCB1, SMARCA2, SMARCA4), and the PCR2 complex, which houses Cohen–Gibson syndrome (COGIS) and Weaver syndrome (WVS) (~4%, EED, EZH2)." (PMID 37762546, 2023).
bladder tumors (8 papers, 2013 to 2025). "This mechanistic convergence aligns with recent reports: ARID1A-mutant bladder tumors exhibit higher TMB and improved ICIs outcomes, and a significant increase in CD4+ T-lymphocyte infiltration has been observed in ICIs responders." (PMID 41438758, 2025). "ARID1A, a subunit of the SWI/SNF complex, is mutated in approximately 20% of all bladder tumors; however, the consequences of this remain poorly understood." (PMID 40170512, 2025). "By analyzing a broad range of tumors, representative of UBC diversity, we find that ARID1A alterations generally occur in FGFR3 wild type, poor-prognosis bladder tumors." (PMID 23650517, 2013).
ductal adenocarcinoma (8 papers, 2013 to 2025). "Gene promoter hypermethylation correlated with reduced ARID1A expression in 86.4% of invasive ductal breast carcinomas." (PMID 41001036, 2025). "Although there was no statistic significance between ARID1A and H2B expression with histological types, we noticed that the 13 cases with ARID1A expression belong to invasive ductal carcinoma and the remaining 2 cases are mucinous carcinoma." (PMID 26904685, 2016). "Among 15 cases with ARID1A and H2B coexpression, 13 are invasive ductal carcinoma and 2 are mucinous carcinoma." (PMID 26904685, 2016). "Twenty-two out of 38 invasive ductal carcinomas in the study (57.9%) revealed ARID1A mRNA low expression by realtime RT-PCR." (PMID 23349767, 2013). "In the low expression group, nineteen out of 22 invasive ductal carcinomas (86.4%) exhibited ARID1A promoter hypermthylation." (PMID 23349767, 2013). "ARID1A mRNA low expression (more than 2-fold decrease) was seen in 57.9% (22/38) invasive ductal carcinomas." (PMID 23349767, 2013). "We demonstrate that promoter hypermethylation was the main culprit for ARID1A mRNA low expression in invasive ductal carcinomas." (PMID 23349767, 2013). "The frequency of ARID1A alterations in patients with ductal adenocarcinoma in this cohort may be characteristic of Asian populations." (PMID 36573306, 2023). "The histology of ARID1A positive cases is invasive ductal carcinoma and mucinous carcinoma." (PMID 26904685, 2016). "However, it cannot be excluded that copy number loss is not the cause for ARID1A gene low expression in invasive ductal carcinomas." (PMID 23349767, 2013).
Intellectual disability (8 papers, 2015 to 2022). "Human genetic studies have identified dysregulation of ARID1A in Coffin‐Siris syndrome (CSS), a congenital disorder characterized by intellectual disability and growth deficiency." (PMID 35854653, 2022). "ARID1A haploinsufficiency has been proposed to cause CSS and intellectual disability, but the neurobiological basis for ARID1A‐haploinsufficiency‐related neurodevelopmental disorders remains unknown." (PMID 36385502, 2022). "To test whether Arid1a is related to intellectual disabilities, we established three mouse models to knockdown or delete Arid1a levels and found that excitatory neurons were the central underlying cause of CSS." (PMID 36385502, 2022). "We demonstrated that haploinsufficiency of Arid1a disrupts the development and function of excitatory neurons and that behavioral phenotypes in mice result in cognitive deficits observed in individuals with intellectual disabilities." (PMID 36385502, 2022). "However, the biological functions and mechanisms of Arid1a in microcephaly and intellectual disability are still unknown." (PMID 34562292, 2021). "For example, BRG1 and BRM mutations (as well as BAF250A/ARID1A and BAF250B/ARID1B mutations) are responsible for Coffin-Siris and Nicolaides-Baraitser syndromes which have similar phenotypic spectrums that include intellectual disability, altered craniofacial features, and distal limb anomalies." (PMID 25544751, 2015).
leukemia (8 papers, 2015 to 2025). A malignant (clonal) hematologic disorder, involving hematopoietic stem cells and characterized by the presence of primitive or atypical myeloid or lymphoid cells in the bone marrow and the blood. "This was congruent with the findings from a previous study that evaluated decreased ARID1A expression in a leukemia cell line with conferred resistance to Fas-mediated apoptosis." (PMID 25975202, 2015). "In another study, where ARID1A and ARID1B were found frequently harboring loss of function mutations in acute promyelocytic leukemia, ARID1B deficiency caused a block in differentiation in this leukemia subtype." (PMID 36941700, 2023). "We next determined the effect of SNDX-5613 on in vivo leukemia-initiating potential of primary PD AML cells harboring MLL-AF9 plus FLT-3 N676T, as well as mutations in KMT2C, KMT2D, NOTCH2, IRF8, ARID1A, VPS13A, and ABCA7, which were determined by whole-exome sequencing." (PMID 35017466, 2022). "Moreover, ARID1A is involved in 2 pathways including the RUNX1 pathway, which plays an important role in the development of leukemia (Pathways section)." (PMID 36035123, 2022).
carcinosarcoma (7 papers, 2014 to 2023). A malignant tumor composed of a mixture of carcinomatous and sarcomatous elements. "Among the microsatellite-stable tumours, ARID1A mutations were unique to carcinosarcomas originating in the ovaries, which may suggest different mutational signatures in carcinosarcomas of different sites." (PMID 25233892, 2014). "Relapsed ovarian/endometrial clear cell carcinoma patients with no ARID1A loss (cohort 2) or patients with other histological subtypes (endometrioid, carcinosarcoma, cervical) (cohort 3) will receive combination therapy (olaparib/ceralasertib)." (PMID 34518240, 2021).
cervical adenocarcinoma (7 papers, 2016 to 2026). An adenocarcinoma arising from the cervical epithelium. "In a prior retrospective study, we identified mutations in FAT1, ARID1A, ERBB2, and PIK3CA in whole-exome sequencing of 15 patients with cervical adenocarcinoma." (PMID 34203201, 2021).
colorectal tumors (7 papers, 2017 to 2025). "This compensatory ARID1B upregulation is commonly seen in poorly differentiated, aggressive cancers, such as colorectal tumors, where ARID1A expression is low and ARID1B is elevated." (PMID 40806597, 2025). "Compared with primary colorectal tumors and normal intestinal mucosa, ARID1A exhibits higher expression in metastatic lesions, but its low expression was associated with worse survival in metastases." (PMID 34414106, 2021). "ARID1A is regulated by DNA methylation and repressive histone modifications and as such likely acts as a potent tumor suppressor gene in some subtypes of colorectal tumors, as it affects many genes’ expression through its role in chromatin remodeling." (PMID 32334542, 2020). "This last hypothesis might be applicable to colorectal tumors, as we identified promoter hypermethylation as a silencing or downregulation mechanism of the ARID1A gene in the CRC cell lines." (PMID 32334542, 2020). "Besides chromatin remodeler genes such as ARID1A, other epigenetic regulatory genes (e.g., lysine methyltransferase genes KTM2C and KTM2D) were often affected by somatic variants resembling our previous findings from LS‐associated colorectal tumors." (PMID 40772756, 2025).
glioblastoma (7 papers, 2018 to 2024). The most malignant astrocytic tumor (WHO grade IV). "In this study, deep targeted sequencing was employed to examine the variance in mutation frequency of the ARID1A gene between primary glioblastoma and non‐glioblastoma, utilizing mismatch repair genes and tumor‐frequent mutation genes as benchmarks." (PMID 38600891, 2024). "In our study, mutations in ARID1A that disrupt its function were predominantly observed in glioblastoma multiforme (GBM)." (PMID 38600891, 2024). "Newly diagnosed glioblastoma cases have also demonstrated a rare incidence rate of 0.7% for ARID1A mutations, which may be linked to an aggressive phenotype." (PMID 37814403, 2023). "RT-treated patients with low ARID1A expression from other tumor entities, such as skin cutaneous melanoma (SKCM), thyroid carcinoma (THCA), and glioblastoma multiforme (GBM), displayed higher expression of CXCL10, IL-6 and CXCL9." (PMID 38587186, 2024).
intrahepatic cholangiocarcinoma (7 papers, 2016 to 2025). A carcinoma that arises from the intrahepatic bile duct epithelium in any site of the intrahepatic biliary tree. "Differently, to date only low expression of ARID1A protein and mRNA were associated to poor prognosis in 57 intrahepatic cholangiocarcinomas analysed by Yang and colleagues." (PMID 29740198, 2018). "Isocitrate dehydrogenase 1/2 (IDH1/2), BAP1, ARID1A and PBRM1 have been reported as the most frequent mutant genes in intrahepatic cholangiocarcinoma (ICC), and their relationships with clinicopathological features and prognosis were researched in this study." (PMID 32293336, 2020).
pancreatic adenocarcinoma (7 papers, 2021 to 2025). "ARID1A is mutated in 10% of intraductal papillary mucinous neoplasms (IPMNs) and 6% of pancreatic adenocarcinoma (PDAC), while KRAS mutations are found in more than 95% of pancreatic ductal adenocarcinoma (PDAC)." (PMID 38275587, 2023). "ARID1A mutations in pancreatic adenocarcinoma had one of the strongest interactions with localised mutational enrichment (interaction P = 5.0 × 10− 4)." (PMID 33941236, 2021). "ARID1A is also one of the most frequently mutated genes in pancreatic adenocarcinoma and in the PCAWG cohort, as 16/24 of tumours carried frameshift or stop-gain mutations that suggest loss of function." (PMID 33941236, 2021). "Second, an increased prevalence of ARID1A mutations was noted in the pancreatic adenocarcinoma." (PMID 39941707, 2025). "In addition, even though mismatch repair deficiency is rare in pancreatic adenocarcinomas, other molecular lesions, such as ARID1A mutations, may confer immune checkpoint inhibitor sensitivity and could become the basis for synergistic combinations." (PMID 36975505, 2023).
pancreatic ductal adenocarcinoma (7 papers, 2017 to 2024). An infiltrating adenocarcinoma that arises from the epithelial cells of the pancreas. "ARID1A loss induces epithelial–mesenchymal transition in pancreatic ductal adenocarcinoma (PDAC) cell lines, with reduced expression of E-cadherin, increased expression of vimentin, enhanced invasive properties, and upregulation of EMT genes." (PMID 38275587, 2023). "Background & Aims: ARID1A is postulated to be a tumor suppressor gene owing to loss-of-function mutations in human pancreatic ductal adenocarcinomas (PDAC)." (PMID 32967217, 2020). "We set out to develop an in vivo model to address the role of the SWI/SNF component ARID1A in pancreatic ductal adenocarcinoma (PDAC), a setting in which mutations in ARID1A or other SWI/SNF components occur in up to 25% of cancer patients." (PMID 30014851, 2018). "Previously, the coincidence of the mutated gene pair ARID1A–APOB and the mutual exclusion of the pair KRAS–APOB were observed in pancreatic ductal adenocarcinoma with significant differences." (PMID 39338204, 2024). "Altered ARID1A was also found to be associated with significantly shorter DFS and OS in the cohort, in concordance with the result of an earlier study enrolling 109 micro‐dissected pancreatic ductal adenocarcinoma cases." (PMID 33350171, 2021). "To model the effect of loss of function mutations in the SWI/SNF subunit Arid1a in pancreatic ductal adenocarcinoma (PDAC) initiation, we directed shRNA triggered, inducible and reversible suppression of Arid1a to the mouse pancreas in the setting of oncogenic KrasG12D." (PMID 30014851, 2018).